IL6 (interleukin 6)
Diseases named in the same sentence as IL6 in open-access papers (continued):
Sharing a sentence is not in itself a finding about the gene and the disease.
Insulin resistance (continued). "Moreover, both short and long sleep durations were related to elevated cortisol, IL-6, and tumor necrosis factor-alpha (TNF-a), which could also partially explain insulin resistance, a central characteristic of MetS." (PMID 38398871, 2024). "The role of IL-6 in type 2 diabetes and insulin resistance has not yet been clarified." (PMID 39051061, 2024). "Furthermore, insulin resistance can augment the levels of inflammatory mediators, such as tumor necrosis factor-α (TNF-α) and interleukin-6 (IL-6), which may exacerbate inflammatory processes within cardiac tissues and impair heart function." (PMID 38956581, 2024). "Given that insulin resistance is a key factor in the development of diabetes, it is plausible to consider whether oxidative stress, along with the elevated release of IL-1, IL-6, and TNF in AS, could lead to insulin resistance, thereby playing a role in the development of diabetes." (PMID 39649224, 2024). "TNF is, in turn, responsible for insulin resistance in humans, and exercise may protect against TNF-induced insulin resistance in part due to its anti-inflammatory effects mediated by muscle-derived IL-6." (PMID 39199416, 2024). "Also, muscle glucose uptake is impaired in IL-6-knockout (IL-6-KO) mice and exercise training fails to improve diet-induced insulin resistance in IL-6-KO mice." (PMID 38474057, 2024). "However, the reconstitution of mast cells in IL-6 or IFN-γ knockout DIO mice did not worsen insulin resistance." (PMID 39606781, 2024). "Additionally, disturbances in lipid metabolism accompanied by gut-derived endotoxins promote the production and release of proinflammatory IL-1, IL-6, and TNF-α, which are able to inhibit insulin receptors signaling, aggravating insulin sensitivity and contributing to insulin resistance worsening." (PMID 37998747, 2023). "Insulin resistance and hyperglycemia can activate the NLRP3 (NOD (nucleotide oligomerization domain)-, LRR (leucine-rich repeat)-, and PYD (pyrin domain)-containing protein 3) inflammasome, leading to the release of cytokines such as interleukin-1, interleukin-6, and tumor necrosis factor-α." (PMID 37375712, 2023). "Also, it has been shown the relative gene expression of pro-inflammatory cytokines such as IL1-β, IL-6, and TNF-α, and apoptosis reduced in insulin resistance-induced HepG2 models after treatment with a combination of metformin and MSC-EXO compared to other groups." (PMID 37153436, 2023). "Probiotics reduce insulin resistance and oxidative stress by increasing SOD (superoxide dismutase), GSH (glutathione), and catalase (CAT) activity, and reduce the expression of inflammatory cytokine tissue necrosis factor (TNF)-α, interleukin (IL)-1β, and IL-6." (PMID 37374359, 2023). "These diets may induce hyperglycemia, which is associated with increased pro-inflammatory cytokines, including IL-6 and TNF-α, leading to insulin resistance by disruptions in insulin signalling and subsequently might increase the risk of the diabetes complications." (PMID 38264289, 2023). "We assessed the gene expression of proinflammatory cytokines, such as IL-1β, IL-6 and TNF-α, as well as mTOR and IKKβ in the adipose tissues of the control and experimental rats in order to assess the ability of C. papaya to mitigate HFD-streptozotocin-incited inflammation and insulin resistance." (PMID 36826001, 2023). "Notably, TNF-α exhibited a dose-dependent effect in inducing insulin resistance, while IL-6 did not contribute to this response." (PMID 37511225, 2023). "In addition, TNF-α induces insulin resistance and lipolysis without affecting fat oxidation, whereas IL-6 has the opposite effect." (PMID 36834025, 2023). "On the one hand, insulin resistance could slow the healing process of the wound, and inflammatory reactions might produce inflammatory factors that influence homeostasis, such as CRP and IL-6." (PMID 37653410, 2023).
Insulin resistance (continued). "Moreover, biochemical indicators such as insulin, insulin resistance index, ADP, GLP-1, LEP, FFA, IL-6, and TNF-α in the serum indicated that GG polysaccharide and FG polysaccharide improved insulin resistance and leptin resistance in diabetic mice, as well as chronic inflammation." (PMID 36235582, 2022). "Additionally, increased ROS is related to diverse metabolic changes, such as increased inflammatory cytokines IL-6 and IFN-γ and insulin resistance, which may modify the immune response and inflammatory process involved in the process of CRC." (PMID 35994506, 2022). "Moreover, IL-6 is required for protection against hepatic inflammation and insulin resistance, and lack of IL-6 reversed the effect." (PMID 35625566, 2022). "Previous studies revealed that the production of lipid metabolites (diacylglycerol), proinflammatory cytokines (TNF-a, IL-1b, IL-6, monocyte chemoattractant protein-1) and cellular stress, including oxidative and endoplasmic reticulum stress, may contribute to FFA-induced insulin resistance." (PMID 35711703, 2022). "Human monoclonal antibody Tocilizumab could inhibit IL-6 signaling selectively, and treatment with Tocilizumab causes a significant reduction of HOMA-IR and insulin resistance in non-diabetic patients with RA." (PMID 36230963, 2022). "These supplements significantly reduced insulin resistance (FBS levels, serum insulin levels (INS), insulin resistance (HOMA‐IR) and HOMA‐B measures), lipid profile (serum cholesterol, VLDL‐cholesterol concentrations, and total cholesterol/HDL levels), inflammation markers (TNF, and IL‐6)." (PMID 35243684, 2022). "In this regard, in our previous study, we also found a significant reduction of insulin resistance, together with increased circulating levels of adiponectin and decreased concentrations of IL-6 in mice with MetS supplemented with CSAT+®, without significant changes in adiposity." (PMID 36139877, 2022). "The results in our study suggest that IL-10 might counteract the negative effects of adiposity-related cytokines, such as IL-6, on insulin sensitivity, which is corroborated by a study in mice where IL-10 co-treatment prevented IL-6 induced insulin resistance." (PMID 35135482, 2022). "HCT can contribute to the release of several proinflammatory cytokines such as interleukin-6 (IL-6) and tumor necrosis factor-α (TNF-α), and previous studies have shown that the latter could contribute to insulin resistance by influencing the insulin signaling pathway." (PMID 35406580, 2022). "There is only little evidence for a possible antihyperglycemic role of IL-6 inhibitors, which may act as antihyperglycemic agents by reducing IL-6-driven insulin resistance." (PMID 35629988, 2022). "Elevated levels of TNF-α and IL-6 could also trigger the synthesis of C-reactive protein (CRP) in the liver, which is a common systemic inflammatory biomarker and invariably correlates with insulin resistance and the pathogenesis of T2DM." (PMID 34955840, 2021). "Pro-inflammatory cytokines, such as interleukin (IL)-12, IL-6, IL-1β, and tumor necrosis factor (TNF) might play a fundamental role in the onset and progression of NAFLD promoting insulin resistance, oxidative stress, hepatic inflammation, cell necrosis, apoptosis, and liver fibrosis." (PMID 34447378, 2021). "Besides, several arachidonic acid metabolites, including PGE2, PGI2, and LXA4, PGE2 and PGI2 can alleviate insulin resistance and improve insulin sensitivity of pancreatic cells; LXA4 can inhibit the production of IL-6, TNF-α, and ROS, thus alleviating inflammation, and has an antidiabetic effect." (PMID 33628839, 2021).
Insulin resistance (continued). "Moreover, IL-6 and TNF may stimulate the breakdown of adipose tissue in an organism through the decrease in fodder consumption, induction of insulin resistance, and direct initiation of lipolysis." (PMID 34316205, 2021). "Moreover, hyperglycemia in diabetes could be controlled by GNPs via improving blood glucose levels, insulin resistance, and liver enzymes, reducing proinflammatory cytokines (include TNF-α, IL-6, and CRP), and enhancing the antioxidant defense enzymes." (PMID 34572503, 2021). "While both TNF-α and IL-6 could be reduced by CCL4 inhibition, it will be interesting to elucidate whether a broader inhibition of systemic inflammation with a specific chemokine, such as CCL4, could improve insulin resistance in clinical diabetes." (PMID 33968046, 2021). "Previous studies showed that lean subjects with insulin resistance have an unfavorable inflammatory profile with elevated tumor necrosis factor-α and interleukin-6, while obese subjects exhibited a comparable inflammatory status regardless of insulin resistance." (PMID 33478525, 2021). "Various proinflammatory factors or cytokines are activated due to insulin resistance, including nuclear factor-kappaB (NF κB), tumour necrosis factor-alpha (TNF-α), amylin and interleukin-6, and these proinflammatory factors may be responsible for the initiation and progression of AP." (PMID 33407178, 2021). "Additionally, the development of insulin resistance is contributed to by pro-inflammatory cytokines such as tumor necrosis factor α (TNF-α), interleukin 1 (IL-1), and interleukin 6 (IL-6), which affect insulin signaling by inhibition of IRS-1 through serine phosphorylation." (PMID 34299269, 2021). "Moreover, adipocyte-derived factors, such as the increased release of TNFα, IL-6, monocyte chemoattractant protein 1 (MCP-1), and additional products of macrophages, and other cells that populate the adipose tissue are involved in insulin resistance." (PMID 34068151, 2021). "Other adipokines, such as resistin, seem to be involved in insulin resistance, while tumor necrosis factor alfa (TNF-α) and IL-6, which may be present at early and late stages of NAFLD, increase expression of SREBP-1c in the liver and further promote insulin resistance." (PMID 34950104, 2021). "Hypertrophic adipocytes can produce pro-inflammatory cytokines, such as IL-6 and TNF, which leads to increased vascular permeability, circulating monocytes and the recruitment of cytotoxic T cells, initiating an inflammatory process that promotes insulin resistance." (PMID 33349270, 2020). "Interestingly, knocking out the receptor for IL-6 in immune cells did not protect from insulin resistance, but disturbed immune homeostasis in mice, suggesting a fine-tuned mechanism." (PMID 33178196, 2020). "For instance, IL-6 increases glucose uptake, lipolysis, and oxidation of FFA and mediates anti-inflammatory effects by inducing expression of cytokines such as IL-10 and inhibiting expression of TNFα, which induces insulin resistance and mitochondrial dysfunction in myocytes in vitro." (PMID 32397353, 2020). "In the same study, IL-6 was the only pro-inflammatory cytokine found to be elevated in wildtype (WT) mice on HFD, compared to adipocyte-specific JNK1-null mice on HFD, and its administration in these JNK1-null mice abolished their protection from HFD-induced hepatic insulin resistance." (PMID 32183037, 2020). "In addition, increased levels of estrogen, progesterone, and adipocyte-derived hormones such as adiponectin, resistin, tumor necrosis factor alpha (TNFα), interleukin-6 (IL6), and C-reactive protein (CRP) are also suggested to play a role in the development of insulin resistance during pregnancy." (PMID 33114711, 2020).
Insulin resistance (continued). "Previous studies have shown that IL-6 can promote liver regeneration and repair, but it can also make the liver sensitive to injury, stimulate hepatocyte apoptosis, induce insulin resistance, and participate in the occurrence and development of non-alcoholic steatohepatitis (NASH)." (PMID 32355577, 2020). "We hypothesize that with the worsening insulin sensitivity in adipose tissue following GSI (i.e. with the previously observed increased in NEFA,) and these newly observed changes in IL-6 secretion, that GSI can lead to a significant degree of localized adipose insulin resistance." (PMID 32603641, 2020). "Interestingly, in vivo studies also confirmed kaempferol ameliorates insulin resistance through inhibiting pro-inflammatory responses, particularly by reducing NF-κβ, TNF-α, and IL-6 levels, and restoring insulin resistance by inhibiting phosphorylation of IRS-1." (PMID 32694996, 2020). "Moreover, gut barrier dysregulations and pathologies promote the production of proinflammatory cytokines (IL-6 and TNF-α), which in turn trigger subclinical inflammation and insulin resistance, shedding light again on the inflammation loop between CRC and diabetes." (PMID 32664279, 2020). "Pro-inflammatory cytokines, such as TNF-α and IL6, stimulate both the c-Jun N-terminal kinase (JNK) and IκB kinase-β (IKK-β)/nuclear factor-κB (NF-κB) pathways, resulting in upregulation of potential mediators of inflammation that can lead to insulin resistance." (PMID 31866871, 2019). "However, it was found that, in obese conditions, adipocytes synthesize and secrete pro-inflammatory cytokines (IL-1, IL-6, and TNF-α), and they are involved in several metabolic pathways related to insulin resistance, ROS production, lipoprotein lipase activity, and adipocyte function." (PMID 31597283, 2019). "However, a recent study showed that blocking IL-6 trans-signaling prevents high-fat diet-induced adipose tissue macrophage recruitment but does not improve insulin resistance." (PMID 31075962, 2019). "Inflammatory cytokines secreted by adipose tissue, such as interleukin 6 (IL-6) and tumor necrosis factor alpha (TNF-α), may exert an endocrine effect to promote insulin resistance by interfering with the insulin signalling pathway, leading to the clinical manifestation of T2DM." (PMID 31485456, 2019). "The metabolic role of IL-6 is extensively studied and there is no consensus if IL-6 is a pro-inflammatory marker directly involved in insulin resistance or an anti-inflammatory marker that increases insulin secretion and beta-oxidation, and improves beta cell function." (PMID 29382850, 2018). "Our data suggested that SXT could suppress the activation of IKKβ/NF-κB signal pathway in liver and decrease the CRP, TNF-α, IL-6, and IL-1β levels in serum of T2DM rats, which were corresponding with the results that insulin resistance was markedly ameliorated in SXT-treated diabetes rats." (PMID 30210342, 2018). "Blocking IL-6 trans-signaling by using gp130Fc soluble protein was found to block adipose tissue macrophage recruitment in high-fat diet-fed mice, but did not inhibit insulin resistance." (PMID 29868016, 2018). "Assessing the inflammatory background main actors in psoriasis and NAFLD, many proinflammatory cytokines, such as IL-1β, TNF-α, and IL6, are in common and may create, sustain, and maintain the three stages of NAFLD, namely, inflammation, insulin resistance, and lipid accumulation." (PMID 29546055, 2018). "Furthermore, NF-κB activation increases the transcription of IL-1β, IL-6, and TNF-α and hyperexpression of these mediators may contribute to insulin resistance." (PMID 29760586, 2018). "In addition, subjects with elevated blood glucose were generally companied with insulin resistance, which may result in higher level of pro-inflammatory cytokines, such as tumor necrosis factor-alpha (TNF-α) and interleukin-6 (IL-6)." (PMID 28432278, 2017).
Insulin resistance (continued). "Therefore, increased TNF-α and/or IL-6 secretion could explain the relationship between elevated serum hs-CRP and insulin resistance." (PMID 28575103, 2017). "Several additional conditions often accompanying the syndrome were also present: insulin resistance (increased plasma insulin), kidney damage (increased plasma creatinine and albuminuria) and inflammation (increased plasma levels of TNF-α and interleukin six (IL-6))." (PMID 28101123, 2017). "Increased circulating levels of TNF-α and IL-6 augment the activity of 11β-HSD-1 resulting in an increase in the production of corticosterone in the adipose tissue, which can lead to abdominal obesity characteristically seen in Indians and those with insulin resistance and type 2 DM." (PMID 28824543, 2017). "Recently, we studied the in vivo role of HGK in immune responses by generating T-cell-specific HGK conditional knockout (T-HGK cKO) mice; we found that these mice displayed higher serum IL-6 levels and spontaneously developed insulin resistance without large weight gain." (PMID 26918832, 2016). "However, not all insulin resistance-related proinflammatory cytokines were different in this study as TNFα and IL-6 were similar in NR and RR mice." (PMID 27577172, 2016). "In addition, IL-6 has strong anti-inflammatory effects and may inhibit TNF-α induced insulin resistance." (PMID 25853572, 2015). "Our data suggest a possible positive role for IL-6 in suppressing the level of TNF-α and MCP-1, in maintaining adipose tissue homeostasis and in preventing the consequences of high proinflammatory cytokine levels, as insulin resistance and other elements of the metabolic syndrome." (PMID 25611388, 2015). "In addition, TNF-α does not induce insulin resistance when IL-6 is down-regulated in adipose tissue." (PMID 24733068, 2014). "Insulin resistance leads to a perturbation in the lipid homeostasis, cytokines, and adipokines production, resulting in increased systemic inflammation, with higher levels of inflammatory markers such as C-reactive protein (CRP), interleukin (IL)-6, and tumor necrosis factor (TNF)-α." (PMID 23762872, 2013). "Both TNF-α and IL-6, two main proinflammatory cytokines released by adipose tissue, can inhibit insulin signalling, and TNF-α may have a crucial role in the development of insulin resistance in type 2 diabetes." (PMID 23590862, 2013). "Moreover, different studies indicate that serum IL-6 levels are a negative indicator of the development of breast cancer in overweight or obese patients with prominent insulin resistance." (PMID 24106481, 2013). "Moreover, reductions in adipose tissue mitochondria do not explain the greater insulin resistance in IL-6−/− mice fed a high fat diet." (PMID 23240005, 2012). "The results demonstrating the close relationship between HOMA index and TLR2 expression in monocytes and inflammatory cytokines such as TNF-α and IL-6 could provide therapeutic interventions against insulin resistance in nondiabetic RA patients." (PMID 23213270, 2012). "Thus, further evaluation of IL-6 levels in people consuming GBC30 is needed, in healthy individuals, individuals experiencing acute infection, in those with chronic inflammatory conditions, insulin resistance, and endothelial dysfunction." (PMID 20331905, 2010). "Elevated blood levels of IL-lβ and IL-6 increase the risk of type 2 diabetes, and lack of IL-lβ decreases the severity of atherosclerosis in ApoE-deficient mice on the C57B1/6 background, a model that develops insulin resistance when fed a Western diet." (PMID 16787541, 2006). "Building on the findings from IL-6 and IL-10 studies, future research should explore whether IL-27 activates gut immune and endocrine pathways to promote GLP-1 secretion, thereby improving insulin resistance and alleviating glucose and lipid metabolism disorders associated with obesity." (PMID 39906735, 2024).